PRL (prolactin)
Diseases named in the same sentence as PRL in open-access papers (continued):
Sharing a sentence is not in itself a finding about the gene and the disease.
tumor (continued). "Long-acting pasireotide and bromocriptine provided biochemical control of growth hormone and prolactin in a patient with plurihormonal pituitary macroadenoma, allowing near-complete tumor excision while restoring pituitary function and avoiding adjunctive radiotherapy." (PMID 30899469, 2019). "It is possible that antidepressants could act differently on reducing the prolactinoma, with worsening prolactin production and improving tumor reduction." (PMID 31202268, 2019). "E. Espinosa reported that Cabergoline treatment could result in the normalization of PRL levels in 68% and in the reduction of 50% in tumor volume in 87% of the giant PRL-oma patients." (PMID 31191457, 2019). "However, the long-term survival rates of both GII-III and GBM patients that were PRL+ were lower than those with PRL- tumours." (PMID 31862900, 2019). "His prolactin levels indicated that the tumor was a prolactinoma." (PMID 31202268, 2019). "PRL has also been reported to promote tumour cell proliferation, angiogenesis and chemoresistance." (PMID 31862900, 2019). "Finally, we addressed potential contribution of androgen receptor (AR) signaling to the mechanisms favoring STAT5-independent tumor progression in aged mice of the Pb-PRL background." (PMID 31269779, 2019). "In patients with prolactinomas, circulating PRL levels usually parallel the tumor size." (PMID 29768629, 2018). "Her MRI showed a suprasellar apoplectic tumour with a prolactin of 30,824 miU/L." (PMID 30014342, 2018). "Steroidogenic factor 1 (SF-1) is expressed in GT, and Pit1 is expressed in tumours derived from the production lines of growth hormone (GH) (somatotroph tumours, ST), prolactin (PRL) (lactotroph tumours, LT) and thyroid-stimulating hormone (TSH) (thyrotroph tumours, TT)." (PMID 29979686, 2018). "MRI showed an enlarging apoplectic tumour despite a prolactin of 63 miU/L." (PMID 30014342, 2018). "Surgery and the subsequent tumor regression also caused a significant decrease in prolactin concentration, although it was not normalized." (PMID 30542321, 2018). "Giant prolactinoma is defined as tumours larger than 40mm with very high prolactin secretion." (PMID 30186640, 2018). "This would be explained by the fact that much of the tumour is necrotic or haemorrhagic and therefore unable to produce the level of prolactin that might be expected of its size." (PMID 30014342, 2018). "Histologically, all the children had prolactin-secreting tumours." (PMID 30014342, 2018). "After treatment for 24 months, prolactin and tumor diameter were significantly reduced." (PMID 30349477, 2018). "They suggested that such overexpression might reflect the host/tumor response or be induced secondary to autocrine/paracrine release of growth hormone and prolactin." (PMID 30453988, 2018). "Furthermore, such patients exhibit increased serum prolactin compared with healthy patients, and magnetic resonance imaging (MRI) can be used to investigate the size and extent of the tumor." (PMID 30407358, 2018). "Thus, treatment of prolactinomas with resistance to cabergoline remains a worrying, but there was a significant decrease in prolactin and tumor decrease by more than 90% with the use of high doses of cabergoline in the long term." (PMID 30542321, 2018). "In the pathological examination, the tumor was positive for GH and PRL (scattered)." (PMID 29587659, 2018). "Also, exogenous estrogen was more effective in increasing pituitary weight, plasma levels of PRL and tumor aggressiveness in the pituitary of AF rats." (PMID 29769550, 2018). "His follow-up showed evidence of tumour reduction and prolactin reduced to ~ 10,000 miU/L." (PMID 30014342, 2018). "In addition to the PA tumor, a pituitary prolactinoma was revealed in the sella turcica, supported by the elevated S-prolactin level in the patient." (PMID 28448514, 2017).
tumor (continued). "However, PRL levels were significantly higher in patients with partial tumor resection (P<0.05); FSH and LH levels were significantly higher in patients with complete tumor resection (P<0.05)." (PMID 29108291, 2017). "However, other positive influences on prolactin production such as stress and the use of some anti-psychotics would still be operative and capable of influencing tumor promotion through this mechanism." (PMID 28422740, 2017). "When approaching benign micro and macroprolactinomas, initial treatment is a dopamine agonist such as cabergoline or bromocriptine, both of which have been shown to reduce tumor size, normalize serum prolactin levels, and restore gonadal function in more than 70-95% of patients." (PMID 27489751, 2016). "The aim of this study was to retrospectively assess in the menopause the effects of the suspension of treatment on PRL levels and on the tumor size in patients with micro and macroprolactinomas diagnosed and treated with dopamine agonists (DA) during their fertile age." (PMID 26909481, 2016). "Additionally, 56% of patients just need low-dose BRC treatment to maintain the long-term normalization of PRL levels and to prevent tumor recurrence." (PMID 27999593, 2016). "We have shown that physical rigidity of the ECM is a major determinant of the spectrum of PRL-induced signals, increasing PRL activation of the tumor progressive FAK/SFK/ERK1/2 signaling cascade in stiff environments through localization of PRLR to focal adhesions." (PMID 27344177, 2016). "Additionally, this environment increases pro-tumor progressive PRL and estrogen cross-talk through SFKs." (PMID 27344177, 2016). "Importantly, all mice within the MDA-MB-231/PRLR treated group failed to develop any detectable tumors throughout the period examined suggesting that PRL abrogates tumor formation in vivo." (PMID 27480353, 2016). "Once the PRL level and tumor volume were adequately controlled, the dose of DA could often be decreased incrementally and then kept at a minimal maintenance dose." (PMID 27999593, 2016). "The high concentrations of estrogen, progesterone and prolactin might account for the significant tumor enlargement during pregnancy." (PMID 26040320, 2015). "DRD2 agonists, among which cabergoline is the most effective and best tolerated, are first-line therapy for prolactinomas as they are effective in controlling clinical symptoms, PRL levels, and tumor volume and are used to a lesser extent in the treatment of ACTH-secreting tumors and NFPAs." (PMID 26733942, 2015). "The high concentrations of estrogen, progesterone and prolactin which promote the growth of ducts and the formation of tubuloalveolar structures might be a reason for the significant tumor enlargement in this period." (PMID 26040320, 2015). "Whether prolactin is involved in the early development or promotes late-stage growth of an established tumor is unclear." (PMID 25887963, 2015). "Pharmacological resistance of PRL-secreting tumors is generally defined as failure to normalize PRL levels, and to achieve tumor size reduction of at least 50%, although this definition is still controversial and a variety of definitions of DA-resistance have been used." (PMID 26733942, 2015). "Hence scientists have been interested in developing therapies for controlling tumor growth through suppression of prolactin production." (PMID 25987887, 2015). "Similarly, for women wishing to breastfeed, an MRI scan should be done to ensure the stability of the tumor within 4–6 weeks of delivery, as DAs will decrease serum PRL levels, subsequently impairing lactation." (PMID 26074878, 2015).
tumor (continued). "Giant prolactinomas typically respond rapidly to dopamine agonist therapy, but may require multimodal therapeutic options including surgery and radiotherapy to achieve normalisation of prolactin and tumour control." (PMID 25520847, 2014). "Adrenocorticotropic hormone (ACTH)- and prolactin (PRL)-secreting tumours are the most common." (PMID 24520294, 2014). "Moreover breastfeeding stimulate the production of prolactin, a hormone that has been reported to have tumour promoting effects." (PMID 24708573, 2014). "The current finding that estrogen, progesterone, and prolactin induce expression of Dab2, a growth and tumor suppressor, may represent a feedback mechanism for growth control." (PMID 25360623, 2014). "These in vivo experiments confirmed the presence of interstitial acidosis and regionally increased glucose uptake and glycolytic metabolism in T47D xenotransplants, and established selective unresponsiveness of GLUT1-positive tumor regions to exogenous human prolactin." (PMID 24004716, 2013). "We therefore hypothesized that GLUT1-positive T47D tumor regions would be resistant to exogenous human prolactin." (PMID 24004716, 2013). "Our patient’s tumor also showed faint PRL immunostaining and yet her serum PRL was normal." (PMID 24119925, 2013). "In addition, we have recently reported that prolactin can suppress a therapy-resistant, tumor-initiating CK5-positive population induced by progestin." (PMID 23758962, 2013). "However, the positive immunostaining for prolactin in addition to GH in an extracranial metastasis from a GH-producing tumor is a unique feature of the case." (PMID 23009369, 2012). "Inferences should also be limited considering the frequent use of the surrogate outcome, prolactin level, as opposed to patient-important outcomes, such as loss of quality of life due to tumor-related and hypogonadal symptoms." (PMID 22828169, 2012). "The clinical signs and symptoms vary according to age, sex, tumor size, and prolactin level." (PMID 21750634, 2011). "Recently, our laboratory demonstrated for the first time that effective growth suppression of prolactin and growth hormone producing tumor cell could be achieved by using curcumin, a natural food additive." (PMID 20405005, 2010). "If PRL levels were affected by tumours or patient stresses, our case–control estimates might be inflated; however, our case–control associations are generally similar to those found in NHS." (PMID 20736944, 2010). "Mean serum PRL levels by tumour characteristics are reported." (PMID 20736944, 2010). "Histological staining indicated that PASC1 tumours indeed expressed human GH, as well as moderate human PRL, whereas only a minority of tumour cells were proliferative based on Ki67 staining, similar to the histology and hormone production features of the primary human tumours." (PMID 19568241, 2009). "The classification of these tumours is usually based on the types of pituitary hormones they produce, such as prolactin (PRL), growth hormone (GH), adrenocorticotropic hormone (ACTH), luteinising hormone (LH), follicle-stimulating hormone (FSH), thyroid-stimulating hormone (TSH), and others." (PMID 19568241, 2009). "The transgenic expression of prolactin results in increased tumour formation in mice." (PMID 19014541, 2008). "For example, prolactin is the predominant driver of tumor development in F344 rats; however, whether this hormone is a causative agent in humans is not clear." (PMID 17805427, 2007). "The present experimental study was designed to assess whether metoclopramide administration has any effect on development of MNU-induced tumours, and evaluate the treatment of goserelin acetate on PRL, TNF alpha and NO expression." (PMID 18045456, 2007). "Therefore, tumours with high levels of prolactin would perhaps be more efficiently treated with additional antiprolactin/prolactin receptor therapies." (PMID 15213724, 2004). "Production of prolactin has been reported with several tumours." (PMID 15617576, 2004).
tumor (continued). "The in vivo elevation of SOCS gene expression may be part of the host/tumour response or a response to autocrine/paracrine GH and prolactin." (PMID 12888825, 2003). "Because oestrogens may counteract the anti-tumour effects of such treatment, the combination of an anti-oestrogen (tamoxifen), a somatostatin analogue (octreotide) and a potent anti-prolactin (CV 205-502) might be attractive." (PMID 9459155, 1998). "This could be explained by the direct effect of calusterone on rat adenocarcinoma compared with the indirect effect of oestradiol-17beta which probably exerts its action by activating the secretion of prolactin which acts on the tumour." (PMID 131571, 1976). "The higher tumour yield in the hypothyroid progesterone-treated rats may have been due to higher circulating levels of prolactin in this group compared with those in the hypothyroid group which received no hormone." (PMID 4738218, 1973). "Moreover, there is a debate regarding the tumor size and invasiveness of GH/PRL positive tumors." (PMID 40421250, 2025). "Importantly, cabergoline may also reduce tumor size in up to a third of patients, and complete shrinkage of mixed GH&PRL-PAs has also been reported for bromocriptine in monotherapy." (PMID 40590355, 2025). "Importantly, in line with the differentiation role of PRL in the breast, PRL mRNA levels were found to be associated with more differentiated tumors, early stage, smaller tumor size, absence of distant metastasis and prolonged relapse-free survival (RFS)." (PMID 40157909, 2025). "Importantly, breastfeeding has not been associated with an increase in tumor size, despite the fact that nipple stimulation can lead to increased prolactin secretion." (PMID 39816925, 2025). "Indeed, studies in mouse models and clinical investigations have demonstrated that autocrine PRL derived from tumor cells could induce and promote BC." (PMID 38898487, 2024). "Consequently, prolactin levels below 162 mU/L (7.6 ng/mL) at withdrawal are still regarded as the goal of long-term cabergoline treatment and, together with maximum tumor size below 3.1 mm, predict remission of prolactin-secreting tumors in the highest percentage of patients." (PMID 39456268, 2024). "DAs not only decrease PRL secretion but also downregulate PRL gene expression in pituitary cells, resulting in a decrease in the number of PRL secretory granules, vacuolation of secretory cells, cell death including apoptosis, and bromocriptine-induced tumor fibrosis." (PMID 38516477, 2024). "In the case of the mildly hyperprolactinemic patient on DA with sign/symptom resolution and whose tumor size is controlled, it is unclear if there is a tangible medical benefit to be gained by further up-titrating DA to achieve strictly numerically normal prolactin levels." (PMID 37711900, 2023). "This systematic review supports the use of a combination of a dopamine agonist with an aromatase inhibitor for a subgroup of male patients with prolactinoma, as the addition of anastrozole or letrozole improved the control of prolactin levels and may lead to shrinkage in tumor sizes." (PMID 36835974, 2023). "It was hard to understand that only the level of prolactin in blood could not be a predicting factor, whereas detection of a prolactin-secreting tumor on IHC staining might reduce the risk of LTLs." (PMID 37886642, 2023). "Moreover, size, tumor volume, and PRL levels were reduced in F344 rats." (PMID 37958702, 2023). "It is reasonable to continue with further dose increase whenever this is followed by a substantial PRL decrease, whereas it is recommended to go back to the lowest dose that caused the lowest PRL levels without increase in tumor size, in order to avoid side effects." (PMID 35000899, 2022).
tumor (continued). "In the case of lactotroph tumor cells, abnormally spliced mRNA derived from the ESRRG gene, which encodes ERRγ, results in a mutant ERRγ protein, which has shown to have an abnormally high affinity for PIT1 and potently enhance PIT1-dependent PRL gene transcription." (PMID 35892862, 2022). "PRL and its receptor may play an onco-modulatory role and promote tumor aggressiveness in OC." (PMID 34358244, 2021). "In addition, a recent clinical trial treating two patients with DA-resistant prolactinomas with lapatinib at a dosage of 1,250 mg/day has reported 78% and 42% PRL suppression respectively with a 22% tumor reduction in the former and a stabilized tumor in the latter." (PMID 33841328, 2021). "Whether these tumor cells can secrete PRL needs to be determined." (PMID 34099636, 2021). "Thus, this study is the first to indicate that PRL might regulate tumor fibrosis and the progression of ccRCC." (PMID 34539753, 2021). "Once the additional validation and optimization steps are accomplished, we foresee that SMI-6 could provide a triple benefit to BC patients with PRL/PRLR-expressing tumors: suppression of tumor growth, inhibition of invasion/metastasis, and enhanced efficacy of standard chemotherapeutic agents." (PMID 34071395, 2021). "In addition to the earlier studies indicating that neutralizing GM-CSF reduced the proliferation, angiogenesis, and colonic epithelial cells (CECs) in neoplasia, our data point out that this factor is also an accessory after the fact along with leptin and prolactin." (PMID 31742371, 2020). "However, it remains unknown whether the other mechanism may also be involved in CAB- and BRC-mediated tumour shrinkage and serum PRL level decrease in prolactinomas." (PMID 31000722, 2019). "Recently, it has been shown that the association of octreotide LAR with cabergoline may improve prolactin concentration and decrease tumor size in some, but not all, cabergoline-resistant prolactinomas." (PMID 30542321, 2018). "Thus, even when the use of aromatase inhibitors deprives a patient of estradiol, prolactin would still be capable of reducing expression of p21 and promoting tumor progression, although prolactin expression would also usually be reduced with aromatase inhibitors." (PMID 28422740, 2017). "Moreover, molecular silent tumours expressing PRL, TSH or GH genes could reduce their size if be treated with cabergoline or somatostatin analogues." (PMID 28692683, 2017). "Thus, it is conceivable that some of EGF actions could result from the activation of PRLR by endogenous prolactin expressed in tumor cells." (PMID 27564112, 2016). "Finally, we provide evidence that PRL-induced pTyr-PAK1 stimulates tumor cell metastasis in vivo." (PMID 27542844, 2016). "Moreover, within the MDA-MB-231/PRLR untreated group only one mouse showed tumor growth that reached a maximum volume of 0.875 mm3 suggesting that mouse PRL while it is described as a weak agonist of the hPRLR, it is sufficient to induce activation of the overexpressed hPRLR." (PMID 27480353, 2016). "Tumor cells in patients with prolactinomas express estrogen receptors; as a result of the increased estrogen level during pregnancy, there can be a substantial increase in the volume of the prolactinoma, with a progressive increase in serum prolactin due to lactotroph cell hyperplasia." (PMID 26074878, 2015). "Pituitary compression by a tumor may present with visual field defects; furthermore, patients in the CD + PRL group were much more likely to have macroadenomas, which are more commonly associated with the development of neurological deficits and visual disturbances." (PMID 25506361, 2014). "Therefore, an acidic tumor environment might facilitate cleavage of full length prolactin into 16 K prolactin." (PMID 24004716, 2013).